GRIN2A (glutamate ionotropic receptor NMDA type subunit 2A)
Diseases named in the same sentence as GRIN2A in open-access papers (continued):
Sharing a sentence is not in itself a finding about the gene and the disease.
neurological disorders (28 papers, 2014 to 2025). "Mutations in GRIN2A can disrupt these processes and often affect children, leading to a variety of neurological disorders." (PMID 39050322, 2024). "While GRIN2A has mainly been studied in neurological disorders, growing evidence indicates cross-talk between neurotransmission and host immunity." (PMID 40918096, 2025). "To unravel the functional contributions of the voltage-dependent Mg2+ block in neurological disease, brain physiology, and behavior, we generated and analyzed heterozygous and homozygous gene-targeted mice with global Grin2a(N615S) expression (Grin2a+/S and Grin2aS/S, respectively)." (PMID 33420383, 2021). "Our findings strongly suggest that not all NMDA antagonists may be of equal clinical utility in treating GRIN2A-mediated neurological disorders, despite a shared mechanism of action." (PMID 34776984, 2021).
cancer (18 papers, 2014 to 2025). A tumor composed of atypical neoplastic, often pleomorphic cells that invade other tissues. "GRIN2A is a subunit of the NMDA glutamate receptor and is recurrently altered by mutation in various cancer types." (PMID 36900209, 2023). "We then looked at the hub-driver genes identified in a previous study of CRC network analyses (Palaniappan, Ramar & Ramalingam, 2016), and found that GRIN2A and EIF2B5 were significantly differentially expressed in the cancer samples (adj.p-values ∼2.14e−37 and 2.32e−13, respectively)." (PMID 39484215, 2024). "Moreover, by using the same evaluation criteria, we identify new biomarkers whose impact on drug response spans multiple cancers, including SALL4, B2M, BAP1, CCDC6, ERBB4, FOXA1, GRIN2A, and PTPRT." (PMID 39083502, 2024). "Alterations in the Ca2+ signaling pathway were observed in nine cancer types and AGTR1 GRIN2A (Glutamate Ionotropic Receptor NMDA Type Subunit 2A), ITPKB (Inositol-Trisphosphate 3-Kinase B), and SLC8A3 (Solute Carrier Family 8 Member A3) were repressed by hypermethylation in six of them." (PMID 32629766, 2020). "For example, AGTR1, GRIN2A, ITPKB, and SLC8A3 were repressed by hypermethylation in six cancer types, and ADCY4, ADCY8, BST1, and PRKCB were inhibited by hypermethylation in five cancer types." (PMID 28060724, 2017). "In addition to known cancer driver genes such as ERBB2 (6% of cases), NRAS (3%), MET (3%), PIK3CA (1%), AKT2 (1%), TSC1 (1%), and ERBB4 (1%), several putative cancer genes were identified, such as PTPRC, SYNE2, GRIN2A, and CDH10." (PMID 24576404, 2014). "Unlike GRIN2A, GRIN2B was not annotated as a cancer driver gene, according to cBioPortal algorithms." (PMID 36768862, 2023).
tumor (16 papers, 2014 to 2025). "GRIN2A (Glutamate Receptor, Ionotropic, N-Methyl D-Aspartate 2A) encodes the GluN2A receptor subunit that has been shown to act as a tumor suppressor, with mutant forms acting in a dominant negative fashion on the wild-type receptor." (PMID 32014051, 2020). "GRIN2A has previously been identified as frequently mutated in tumor samples, leading to a hypothesized involvement of GRIN2A in tumorigenesis." (PMID 40565021, 2025). "Of 19 tumor samples tested, four (21%) carried five non-synonymous mutations in GRIN2A." (PMID 24455489, 2014). "The expression of GRIN2A is in general higher in normal tissues compared to the respective tumor tissue." (PMID 40565021, 2025). "Indeed, the depletion of wildtype GRIN2A in somatic samples has been shown to increase cell proliferation in vitro, suggesting GRIN2A to be a tumor suppressor gene." (PMID 40565021, 2025). "However, as germline null variants of GRIN2A are ubiquitously present in all tissues, a loss of NMDA receptor functionality would be expected in all tissues, not limited to potential tumor tissues of individuals carrying a pathogenic germline variant." (PMID 40565021, 2025). "The previous studies on somatic variants in GRIN2A assessed tumor samples without assessing germline variation, while studies on pathogenic germline variants did not consider somatic variants." (PMID 40565021, 2025). "The unexpected genetic variation in GRIN2A in tumor samples led to the hypothesis that GRIN2A might serve as a proto-oncogene." (PMID 40565021, 2025). "Original tumor tissue is no longer available to confirm that these contained GRIN2A mutations found in cell lines, but an error in cell line authentication is extremely unlikely." (PMID 24455489, 2014). "Clinical characteristics for all patients, according to the presence or absence of GRIN2A mutations in tumor-derived cell lines." (PMID 24455489, 2014). "We identified three tumor suppressors: CTNNA1 (C772 and vicinal cysteine C767), GRIN2A (C320 and proximal C87), and CBFB (C25 and proximal C124)." (PMID 37085483, 2023). "None of the analyzed tumor entities showed a significantly higher expression of GRIN2A when compared to normal tissue, where the expression was in some cases even higher than in the tumor sample." (PMID 40565021, 2025). "No tumor sample showed a significantly higher expression of GRIN2A than the matched non-disease tissue." (PMID 40565021, 2025). "The expression of GRIN2A is lower in tumor samples compared to in non-diseased tissues." (PMID 40565021, 2025).
psychiatric disorder (12 papers, 2013 to 2026). A disorder characterized by behavioral and/or psychological abnormalities, often accompanied by physical symptoms. "This approach pointed to cortical excitatory neurons as a potentially crucial cell type in psychopathology and identified key genes such as GRIN2A as potential targets for further research and treatment development in psychiatric disorders." (PMID 40253403, 2025). "We further measured the mRNA levels of a number of genes known to be involved in the pathology of psychiatric disorders, including Bdnf, Fosb, Drd1/2, Grik2, Hdac1/9v, and Grin2a/b." (PMID 36582489, 2022). "Indeed, NMDA receptors, including GRIN2A, are important for the function of PV+ interneurons, and undergo changes during development that may make these cells particularly sensitive to perturbation in psychiatric disease." (PMID 36914641, 2023).
neurodegenerative disease (8 papers, 2017 to 2025). A disorder of the central nervous system characterized by gradual and progressive loss of neural tissue and neurologic function. "Four genes inside these degenerative diseases also showed differential expression among ages: CTCL (G50 vs G60), CALM1 (G50 vs G70), GPR183, and GRIN2A (G60 vs G70)." (PMID 33576945, 2021).
infection (6 papers, 2015 to 2025). The state of being infected such as from the introduction of a foreign agent such as serum, vaccine, antigenic substance or organism. "We also identified a protein GluN2A encoded by Grin2a was continuously expressed at high levels after infection." (PMID 36061859, 2022). "We identified that the expression of Glutamate receptor ionotropic, NMDA 2A (gene symbol: Grin2a) continued to increase at 3- and 7-days post-infection." (PMID 36061859, 2022).
movement disorder (5 papers, 2012 to 2024). Neurological conditions resulting in abnormal voluntary or involuntary movement, which may impact the speed, fluency, quality and ease of movement. "In a population with chronic mental illness, various tag SNPs in 7 candidate genes (GRIN2B, GRIN2A, HSPG2, DRD3, DRD4, HTR2C, and NQO1) reached nominally significant (p≤0.05) associations with drug-induced movement disorders." (PMID 23226551, 2012).
GRIN2A also shares sentences with these, for which no sentence is quoted: ischemic stroke (17 papers); Cerebral ischemia (13); ischemia (10); encephalitis (8); speech disorder (8); lupus (7); language disorder (6); Seizure (6); Hypertension (5); Angelman syndrome (4); attention deficit-hyperactivity disorder (4); Dravet syndrome (4); migraine (4); Sepsis (4); alcoholism (3); brain disorder (3); glioblastoma (3); injury (3); mood disorder (3); Rett syndrome (3); status epilepticus (3); autoimmune encephalitis (2); cognitive disorder (2); cognitive- (2); gastric cancer (2); genetic disorder (2); Hyperammonemia (2); hyperhomocysteinemia (2); inflammation (2); language delay (2).
A further 83 diseases each share a sentence with GRIN2A in 2 papers or fewer.